CD4 (CD4 molecule)
Diseases named in the same sentence as CD4 in open-access papers (continued):
Sharing a sentence is not in itself a finding about the gene and the disease.
tumor (continued). "Comparative analyses showed that the cell subcluster distributions of CD4+ T cells, CD8+ T cells, memory B cells, stem-like epithelial cells, and tumor-associated macrophages were significantly increased in the LRP1B high-expression group." (PMID 40170839, 2025). "VEGFR is expressed in T-cells, including CD4+ T-cells, CD8+ T-cells, regulatory T-cells (Tregs), and myeloid cells, including dendritic cells (DCs), tumor-associated macrophages (TAMs), and myeloid-derived suppressor cells (MDSCs) as well as endothelial cells." (PMID 39985645, 2025). "The results showed that pan‐lactylation levels were significantly higher in tumor cells and CD8+ T cells compared to CD4+ T cells and tumor‐associated macrophages (TAMs)." (PMID 40552757, 2025). "To enable in vivo interactions between tumor cells and host-derived T cells, we orthotopically injected CD4-Cre:RiboTag mice with E0771-GFP-RPL10a cells." (PMID 40389477, 2025). "For example, regulatory T cells (Tregs) promote tumor growth by suppressing CD4+ and CD8+ T cell activity." (PMID 40191727, 2025). "CD4+T cells play an important role in regulating immune responses, and their activity can affect the angiogenesis process in the tumour microenvironment." (PMID 39865437, 2025). "The E743–77-pulsed bm12 mBMDC vaccine is dependent on both CD8+ and CD4+ T cells, but CD4+ T cell depletion at the later stage of TC-1 tumor growth enhances the efficacy." (PMID 40857404, 2025). "Loss of F4/80 TAMs was accompanied by close spatial localization of CD4/CD8+ T cells to tumor cells following the triple combination." (PMID 40568104, 2025). "Treatment with anti-CD4 Th2 neutralizing antibody leads to a significant reduction in tumor formation." (PMID 39806421, 2025). "The tumor cells release interferon-γ (IFN-γ) in response to CD4, Type 1 T helper (Th1), and activated T cells, which upregulate the production of PD-L1, shutting the T cells down." (PMID 40597782, 2025). "Conversely, IDH1+ iCCA had closer spatial interactions between CD4+ T cells and tumor cells as compared to the other molecularly defined groups (p<0.001)." (PMID 39969434, 2025). "Looking at the subtypes of CD4+ cells, Th cells and CD4+ central memory T cells typically contribute to tumor-specific adaptive immunity." (PMID 39860614, 2025). "In this study, we observed that CD4+ T cells in tumor tissues exhibited upregulation of exhaustion-related molecular markers, while CD8+ T cells were predominantly expressed in adjacent normal tissues." (PMID 40740774, 2025). "It provides a comprehensive overview of CD4+ T-cells’ diverse roles in tumor suppression and promotion, as well as innovative NDDS-based strategies to enhance therapeutic outcomes." (PMID 40860882, 2025). "While CD8+ T cells are widely regarded as the primary target for immunotherapeutic interventions due to their well-established role in anti-tumor immunity, recent studies have identified that CD4+ T cells exhibit a cytotoxic program." (PMID 41230345, 2025). "This was further supported by the qualitative finding that in the tumor with disease progression, there was an increased distance between tumor cells and CD4+ or CD8+ T cells, compared with the tumor with PR." (PMID 41171165, 2025). "As a previous study, c-Rel, as a subunit of NF-κB, regulates the transcriptional landscape of activated Tregs and restricts its anti-tumor responses of CD4+ T cells." (PMID 39998561, 2025). "In chronic infections (e.g., HIV) and the tumor microenvironment, the auxiliary function of CD4+ T cells is dysregulated, and they cannot provide effective assistance to CD8+ T cells." (PMID 40305201, 2025). "Combining RAS(ON) and CDK4/6 inhibition with a CD40 agonist results in durable regressions and CD4 T cell–dependent tumor-immune equilibrium." (PMID 40299790, 2025).
tumor (continued). "Tumor tissues showed a significant decrease in adaptive immune cells, including plasma cells and memory B cells, accompanied by an increase in activated CD4+ memory T cells and a reduction in resting CD4+ memory T cells." (PMID 39940699, 2025). "Beyond mPR analysis, we also constructed a nomogram model incorporating MVI, tumor capsule integrity, and CD4+ T cell density in the CT region." (PMID 41212769, 2025). "VEGF antibodies, when used alongside a tumor vaccine that promotes granulocyte–macrophage colony-stimulating factor secretion, have been shown to reduce the quantity of CD4 + CTLs and enhance vaccine efficiency." (PMID 40167762, 2025). "CD4+ T cells are primarily localized around the tumor margins, whereas CD/8+ T cells predominate within the tumor core." (PMID 41194936, 2025). "The TCR‐mediated recognition of a cognate antigen on MHC class II molecules expressed on the cell surface of APCs or tumor cells and the stimulation by specific cytokines influence the differentiation of CD4+ T cells." (PMID 40257446, 2025). "In the context of MIBC, CD19+ tumor-infiltrating B cells function as APCs, which are essential for activating CD4+ tumor-infiltrating T cells (TIT)." (PMID 40427030, 2025). "CD8+ and CD4+ T cells are crucial for tumor elimination, but their function is often suppressed within the TME." (PMID 40427030, 2025). "On the other hand, in the HCC microenvironment, IL-22 is mainly secreted by CD4+ T cells and accelerates tumor progression by promoting angiogenesis and immune escape." (PMID 41562076, 2025). "In the context of B2M KO, the activation of CD4+ T cells and NK cells can overcome resistance to PD-1 blockade therapy to enhance anti-tumor efficacy." (PMID 40191187, 2025). "An disparity between” pro- and anti-tumor CD4+ T-cell subsets can be the consequence of dysregulation of this pathway, which can affect the progression of cancer and the effectiveness of therapy." (PMID 40860882, 2025). "Further validation using matched tumor samples confirmed decreased levels of tumor-infiltrating lymphocytes, CD4+ and CD8+ T cells, elevated M2 macrophages, and higher programmed death-ligand 1 (PD-L1) expression in the IMPC group." (PMID 40821778, 2025). "To test this proposition, we depleted CD4+ T cells in mice bearing GSC005 tumor prior to treatment with M002 or saline." (PMID 39885128, 2025). "Naïve CD4+ T cells, when activated by tumor antigen-primed APC and exposed to various cytokines, can differentiate into different subsets, such as T-helper cells: Th1, Th2, Th9, Th17, Th22, and T-regulatory (Treg) cells." (PMID 41019045, 2025). "This analysis includes the tumor microenvironment, encompassing the infiltration of immune cells such as CD4+ and CD8+ lymphocytes, macrophage polarization, and increases in certain metalloproteinases (MMP-2 and MMP-9)." (PMID 41516122, 2025). "Within the TME, two distinct clusters were identified: Cluster 1, associated with poor prognosis, exhibited higher gene alterations, greater tumor heterogeneity, and increased infiltration of M0 macrophages and resting memory CD4 T cells." (PMID 39857718, 2025). "This review highlights the critical role of CD4+ T-cells in cancer immunology, demonstrating their dual function as both tumor-suppressing and tumor-promoting agents." (PMID 40860882, 2025). "To elucidate the relative contributions of CD4+ and CD8+ T cells to the anti-tumor response, we employed α-CD4 and α-CD8 antibodies to block these cell populations during CR108 + OVA treatment." (PMID 40606756, 2025). "We detected a correlation between elevated levels of FAM111B expression and the increased infiltration of CD8+ T cells, CD4+ T cells, and CD4+ Teff cells in both total and tumor tissues by the mIF technique." (PMID 40564014, 2025).
tumor (continued). "The results showed that CD4 was highly expressed in paracancerous tissue, while PD‐L1 was highly expressed in tumor tissue." (PMID 39574357, 2025). "Among CD4+ T-cells, only the Th1 subset promotes anti-tumor response, as Th2 promotes tumor development." (PMID 40427098, 2025). "Here, we showed that impairing autophagy selectively in CD4+ T cells is sufficient to increase anti-tumor responses by CD8+ T cells." (PMID 40977681, 2025). "Induces tumor-specific CD4+ and CD8+ T cells capable of migrating to distant sites and exhibiting antitumor activity." (PMID 41450920, 2025). "Compared with PBS and untreated controls, Bgrp78 cell injection resulted in an enhanced tumor progression, PD‐L1 upregulation on intratumoral B cells and less tumor infiltration of effector CD4+ T cells." (PMID 40936109, 2025). "TIBs can present tumor antigens to CD4+ TILs, modulating their phenotypes into activated, antigen-related, and non-responsive subtypes, with activated TIBs linked to effector T cell responses." (PMID 40787464, 2025). "In pancreatic ductal adenocarcinoma (PDAC) models, reduced CD73 expression leads to decreased MDSC populations and lower adenosine levels, thereby enhancing anti-tumor immune responses by increasing IFN-γ production by CD4+ and CD8+ T cells." (PMID 39990210, 2025). "Tumor-infiltrating CD4+ T28zT2 T cells are enriched with TCF-1+IL7R+ memory-like T cells, express NKG2D, and downregulate T cell exhaustion markers, including PD-1 and LAG3." (PMID 40107245, 2025). "These novel aspects collectively support the clinical utility of evaluation using the 73 − 10 IHC-detected PD-L1 expression with CD4+ T-cells playing a key role in the tumor immune response in progressive HNSCC." (PMID 40392349, 2025). "To identify the specific T cell subset that play a major role in the anti-tumor activity, we performed depletion studies using anti-CD4 and anti-CD8 antibodies to selectively deplete CD4+ T and CD8+ T cells, respectively." (PMID 40814015, 2025). "Knocking down S100A11 only in tumor cells decreased a subset of CAFs and increased CD4+ T cells, but improvements in tumor volume and CD8+ infiltration were limited." (PMID 41514658, 2025). "This supports our data which shows that the CD4+/CD8+ ratio is elevated to 5.2 ± 0.6 in non‐stressed tumour‐bearing mice (CANTumor) compared to 2.6 ± 0.5 in mice in which tumours spontaneously regressed (CANRegress)." (PMID 40172096, 2025). "Memory CD4+ T cells help maintain long-term immunity, while Th2 cells are involved in humoral immunity and can influence the tumor microenvironment by modulating the activity of other immune cells." (PMID 40458414, 2025). "The lack of significant differences in tumor growth between fully Nlrp3-deficient mice and CD4Nlrp3fl/fl mice that we observed suggests a predominant role of NLRP3 in CD4+ T cells during tumor progression." (PMID 40195474, 2025). "The PD-1 expression was increased on conventional CD4 T cells, indicating that this T-cell subset also contained some tumor-reactive cells." (PMID 40897471, 2025). "CD4+ T cells aid the anti-tumor CTL response primarily through their help to DCs for better CTL priming or production of cytokines, including IL-2 and IFN-γ to promote CTL survival, proliferation, and/or effector function." (PMID 41542091, 2025). "Then, we focused on evaluating CD4+ T cells infiltration, given their important role in orchestrating the immune response within the tumor microenvironment." (PMID 40037158, 2025). "This review explores the phenotypic and functional diversity of TILs—including CD8+ cytotoxic T cells, CD4+ helper T cells, regulatory T cells, B cells, and natural killer (NK) cells—and their dynamic interactions within the tumor microenvironment (TME)." (PMID 40475782, 2025). "In general, mice treated with ACM‐Trp2 + ACM‐CpG had higher frequencies of CD8+ and CD4+ T cells in the blood, skin drLN, and tumour as compared to mice treated with free Trp2 + free CpG." (PMID 39873184, 2025).
tumor (continued). "RYR2 level was negatively correlated with tumor purity and positively correlated with the infiltration of B cells, CD4+ T cells, CD8+ T cells, neutrophils, macrophages, and dendritic cells." (PMID 40200715, 2025). "At day 10 after the first treatment, VVL-TD-RFP treatment significantly increased tumor infiltration of CD4+ T cells, compared with both VVLΔTKΔN1L and PBS treatment." (PMID 40350204, 2025). "Immunogenic chemotherapy has been shown to enhance the efficacy of ICIs by promoting tumor infiltration of CD4+ and CD8+ T cells while attenuating the activity of immunosuppressive populations such as Tregs." (PMID 41320679, 2025). "After a series of processing steps, 1279 tumor-infiltrating CD4+ T cells were retained and subsequently segregated into two groups based on their tissue of origin." (PMID 41008548, 2025). "Among the activated T cells, a significant proportion consists of naive CD8+ T cells and central memory CD4+ T cells, indicating that photothermal tumor ablation fosters a robust anti-tumor immune memory." (PMID 40688079, 2025). "Upon IL-2 binding to the high-affinity IL-2 receptor, CD4 + CD25 + Tregs competitively inhibit the immune response to tumor cells." (PMID 40420174, 2025). "Depletion of CD8+ T cells abrogated the tumor growth difference between WT and Gsdmd–/– mice, despite the functional impairment in GSDMD-deficient CD4+ T cells and NK cells." (PMID 40759573, 2025). "Previous studies have demonstrated that abnormal tryptophan (Trp) metabolism promotes tumor progression by suppressing the cytotoxic activities of multiple immune cells, e.g., CD4+ and CD8+ T cells." (PMID 40365295, 2025). "Temporal coordination not only improved antigen cross-presentation but also strengthened cytotoxic T cell response, as evidenced by increased CD8+ T cell infiltration and elevated CD8+/CD4+ T cell ratios within tumor tissues." (PMID 40680115, 2025). "The authors demonstrated that CD4+ ICOS+ T cells constitute a subset of effector Th1 cells specific to tumour antigens." (PMID 39325360, 2025). "By simultaneously activating the tumor antigen-specific CD8+ and CD4+ T cells, AP-EVs enhance the overall anti-tumor response." (PMID 40504376, 2025). "In summary, B7-H3 interacts with the TME through multiple pathways, suppressing the activation and proliferation of antitumor cells such as CD4+ T cells while accelerating tumor cell growth." (PMID 41463642, 2025). "CD4 T cells are frequently arranged in rosette-like structures tightly encircling H/RS cells, likely creating a protective niche that favors tumor survival." (PMID 41256864, 2025). "The vaccine elicits a synergistic immune triad, including cytokine polyfunctional CD4+ Th1 cells, epitope spreading, and antibody response, contributing to effective tumor control." (PMID 40543509, 2025). "Ectopic CIITA/MHC-II expression reprograms tumor microenvironments by displacing immunosuppressive macrophages and neutrophils with activated CD4+/CD8+ T cells, bolstering antitumor immunity." (PMID 40861816, 2025). "Cytokine signaling and APC activation lead to the cross-presentation of TAAs to T cells in lymph nodes, expansion of tumor-specific CD4+ and CD8+ T cells, and infiltration of cytotoxic T lymphocytes (CTLs) into the tumor." (PMID 40699667, 2025). "We used flow cytometry to quantify the levels of p4E-BP1, a downstream effector of mTOR signaling, within CD45−CD98+ MC38 tumor cells, CD4+ T cells, and CD8+ T cells." (PMID 41160695, 2025). "Estrogen has been shown to facilitate anti-tumor Th1 differentiation and encourage the differentiation of tolerogenic Tregs in CD4+ T cells." (PMID 40303343, 2025). "HPV– HNSCCs have a more immune-suppressed TME, with high frequencies of PD-1–expressing CD4+ Th1 cells, accumulation of tumor-associated macrophages (TAMs) and MDSCs, and high MHC expression and tumor immunogenicity of tumor antigens." (PMID 40231472, 2025).
tumor (continued). "An alternative perspective posits that APOBEC activity fosters an immunologically hot tumor microenvironment, triggering antigen-specific adaptive immunity mediated by CD4+ T cells." (PMID 40356722, 2025). "Probiotic-treated immunocompetent mice showed tumor growth suppression, while prebiotics increased Tumor Infiltrating Lymphocytes (TILs), particularly effector CD4+ and CD8+ T-cells, and activated dendritic cells (DCs)." (PMID 40565936, 2025). "Functional analysis revealed its role in reshaping the tumor immune microenvironment by promoting immune cell infiltration, including M1 macrophages, activated CD4+ T cells, and follicular helper T cells." (PMID 40176817, 2025). "Key subsets of TILs include CD8+ cytotoxic T lymphocytes (CTLs), CD4+ helper T cells, regulatory T cells (Tregs), B cells, and natural killer (NK) cells—each playing distinct roles in shaping tumor immunity." (PMID 40475782, 2025). "In HR-WT tumors, however, the level of cell-cell interaction between tumor cells and CD4+/CD8+T cells is relatively diminished." (PMID 40830526, 2025). "Re-activating the immune system typically requires exogenous antigen-presenting cells (APCs), which present tumor-associated antigens to cytotoxic (CD8+) and helper (CD4+) T cells via major histocompatibility complex (MHC) molecules." (PMID 40573922, 2025). "On the basis of the on-treatment CD4+ T cell densities at the tumor core and margin, we differentiated T cell–enriched (n = 9), T cell–excluded (n = 11), and T cell–deserted tumors (n = 15)." (PMID 40561008, 2025). "Activated granzyme B (GzmB)-expressing CD8+, CD4+ TEM and CD4+ Treg cells were also abundant (91%, 37% and 27%, respectively) in the posttreatment tumor." (PMID 40016450, 2025). "Administration of these CAR-T cells augments antigen presentation to host CD4+ T cells at tumor site in a CXCR3-dependent manner." (PMID 40612946, 2025). "In vivo studies showed that the HPV-DC vaccine formulated with GUPS-AuNPs as carriers effectively suppressed tumor growth, elevated the populations of CD4+ T and CD8+ T cells in the spleen, and induced a robust antigen-specific immune response." (PMID 41012548, 2025). "Conversely, natural killer (NK) cells, cytotoxic cluster of differentiation (CD) 8+ T cells, and proinflammatory CD4+ T cells with the T-helper type 1 (Th1) phenotype interact to prevent pro-tumor effects and provide effective anti-tumor responses." (PMID 40869156, 2025). "The number of Foxp3+ cells in the control group determined by IHC was slightly higher than that of CD4+cells, likely due to the heterogeneous distribution of Foxp3+ cells within the tumor tissue." (PMID 40343532, 2025). "Studies show that CD4+CD25+Foxp3+ regulatory T cells (Tregs) are crucial in facilitating tumor immune evasion." (PMID 41438510, 2025). "Traditional vaccines face challenges in sustaining antigen presentation and efficiently stimulating both CD4+ and CD8+ T cell responses, especially with neoantigens derived from tumor mutations." (PMID 40429669, 2025). "Results indicated that blocking CD8+ T cell activity significantly inhibited the anti-tumor effect of the combination treatment, while blocking CD4+ T cells had a relatively smaller impact." (PMID 41229436, 2025). "As the tumor-infiltrating CD4+ cell population was elevated in oligo-synchronous BM, we further investigated the frequency of regulatory T cells (Tregs) defined by FoxP3 expression." (PMID 40346687, 2025). "Most studies involving tumor cells transfected with GM-CSF have reported an increase in the number of antigen-presenting cells, macrophages and/or dendritic cells and CD4+ and CD8+ T-cells within the tumor." (PMID 40507861, 2025). "Mice were treated with CD4- or/and CD8α-specific antibodies at day 19 post tumor inoculation, and then underwent tumor resection at day 21, followed by NK cell therapy during days 24–31." (PMID 39835538, 2025).